MINDY1 (MINDY lysine 48 deubiquitinase 1)
Description:
Hydrolase that can specifically remove 'Lys-48'-linked conjugated ubiquitin from proteins. Has exodeubiquitinase activity and has a preference for long polyubiquitin chains. May play a regulatory role at the level of protein turnover.
Synonyms: FAM63A; FLJ11280; MINDY-1
Tractability: Small molecule: a structure with a bound ligand is known. PROTAC: ubiquitination databases record sites on it.
Gene: Protein-coding gene on chromosome 1 (150,995,125 to 151,008,376, reverse strand). Ensembl gene ENSG00000143409.
Subcellular location (Human Protein Atlas): Nucleoplasm
Gene Ontology:
Molecular function: cysteine-type carboxypeptidase activity; cysteine-type deubiquitinase activity; K48-linked deubiquitinase activity; K48-linked polyubiquitin modification-dependent protein binding
Cellular component: nucleoplasm
Genetic constraint (gnomAD): Loss-of-function variants: 50 observed, 56.37 expected, observed/expected ratio (o/e) 0.89, 90% interval 0.71 to 1.12. The upper end of that interval is the gene's LOEUF score, 1.12, which puts it in group 4 of 6, group 1 being the genes least tolerant of losing a copy. Missense variants: 484 observed, 595.78 expected, observed/expected ratio (o/e) 0.81, 90% interval 0.75 to 0.88. Synonymous variants: 231 observed, 242.69 expected, observed/expected ratio (o/e) 0.95, 90% interval 0.85 to 1.06.
Homologues: Orthologues: chimpanzee MINDY1 (99% identical), macaque MINDY1 (93% identical), pig MINDY1 (88% identical), mouse Mindy1 (86% identical), dog MINDY1 (84% identical), rat Mindy1 (82% identical), guinea pig MINDY1 (82% identical), rabbit MINDY1 (64% identical), tropical clawed frog mindy1 (59% identical), zebrafish mindy1 (55% identical), Caenorhabditis elegans Y55F3AM.9 (26% identical). Paralogues in human: MINDY2 (52% identical).
Diseases named in the same sentence as MINDY1 in open-access papers:
MINDY1 is named in the same sentence as 10 diseases in open-access papers, as found by Europe PMC text mining. Sharing a sentence is not in itself a finding about the gene and the disease. The quoted sentences say what the papers report.
bladder cancer (5 papers, 2021 to 2025). "Current research indicates that MINDY1 is associated with breast cancer, bladder cancer, and HCC, and promotes their progression." (PMID 40607251, 2025). "In bladder cancer, MINDY1 has been shown to interact with YAP in a deubiquitination activity-dependent manner, deubiquitinating and stabilizing YAP199." (PMID 40607251, 2025). "Overexpression of YAP abrogated the MINDY1 depletion-induced inhibition of cell proliferation in bladder cancer cells." (PMID 37215134, 2023). "Our data further demonstrated that MINDY1 depletion dramatically decreased the proliferation bladder cancer cells." (PMID 34315490, 2021). "In the present study, we examined the role of MINDY1 in bladder cancer cells and identified MINDY1 as the deubiquitinase to mediate YAP deubiquitination." (PMID 34315490, 2021). "Results of immunostaining demonstrated that YAP and MINDY1 colocalized both in the nucleus of bladder cancer cells." (PMID 34315490, 2021). "The analysis of public available data based on TCGA indicated that MINDY1 was amplificated in bladder cancer." (PMID 34315490, 2021). "Genomic analysis of all the MINDYs in human bladder cancer samples revealed MINDY1 amplification was observed in 12% of cases." (PMID 34315490, 2021). "Consistently, silencing of MINDY1 reduced proliferation of bladder cancer cells." (PMID 37215134, 2023). "However, MINDY1 DUB activity promotes the proliferation of bladder cancer cells by stabilizing MINDY1 interaction partner YAP protein and critical transcriptional regulator of the Hippo pathway." (PMID 37892185, 2023). "Our results demonstrated that depletion of MINDY1 significantly decreased cell proliferation and increased the population in G1 phases, indicating that MINDY1 may regulate G1 to S transition in bladder cancer cells." (PMID 34315490, 2021). "We next examined the role of MINDY1 in regulating bladder cancer proliferation." (PMID 34315490, 2021). "MINDY1 depletion significantly decreased bladder cancer cell proliferation." (PMID 34315490, 2021). "MINDY1 could be a possible biomarker and therapeutic target for bladder cancer." (PMID 37215134, 2023). "MINDY1 may be a potential target for bladder cancer intervention." (PMID 34315490, 2021). "Our data suggest that MINDY1 may drive bladder cancer progression via YAP expression." (PMID 34315490, 2021). "Downregulation of MINDY1 disrupted the YAP stabilization and inhibited the expression of YAP downstream genes, such as CTGF, CYR61 and ANKRD1 in bladder cancer." (PMID 37215134, 2023). "In general, our findings establish a previously undocumented catalytic role for MINDY1 as a deubiquitinating enzyme of YAP and provides a possible target for the therapy of bladder cancer." (PMID 34315490, 2021). "Depletion of MINDY1 decreased the YAP protein level and the expression of YAP/TEAD target genes in bladder cancer, including CTGF, ANKRD1 and CYR61." (PMID 34315490, 2021). "To determine the mechanism of MINDY1 in regulating bladder cancer cell proliferation by stabilizing YAP, we performed rescue experiments by ectopic expressing YAP in MINDY1 knockdown T24 cells." (PMID 34315490, 2021). "To further study the relationship of MINDY1 and YAP in bladder cancer, we examined the expression of MINDY1 and YAP in bladder cancer tissues using tissue microarrays (115 bladder cancer specimens)." (PMID 34315490, 2021). "In the present study, we found that MINDY1 was a possible deubiquitinase responsible for YAP deubiquitination and stabilization in bladder cancer." (PMID 34315490, 2021). "We observed an intimate correlation between MINDY1 expression and YAP protein level in human bladder cancer samples." (PMID 34315490, 2021). "Immunohistochemistry staining showed a significant positive correlation between MINDY1 and YAP protein level in bladder cancer tissues." (PMID 34315490, 2021).
bladder cancer (continued). "In the present study, we identified MINDY1, a DUB enzyme in the motif interacting with ubiquitin-containing novel DUB family, as a bona fide deubiquitylase of YAP in bladder cancer." (PMID 34315490, 2021). "In addition, we detected the MINDY1 protein levels in four bladder cancer cell lines (5637, UM-UC-3, T24 and BIU-87) and immortalized normal uroepithelial cell line (SV-HUC-1), exhibiting an upregulation tendency of MINDY1 in bladder cancer cell lines." (PMID 34315490, 2021). "Overall, our study has demonstrated that MINDY1 is a novel deubiquitinating enzyme of YAP and may prove to be a potential target for bladder cancer intervention." (PMID 34315490, 2021).
breast carcinoma (5 papers, 2021 to 2025). "In human breast cancer tissues, there is a positive correlation between estrogen receptor α (ERα) and MINDY1 protein levels, and high expression of MINDY1 is associated with poor prognosis." (PMID 40607251, 2025). "MINDY1 has been shown to maintain the stability of programmed death-ligand 1 (PD-L1), thereby facilitating the immune escape of breast cancer." (PMID 41179305, 2025). "In human breast cancer cells, MINDY1 stabilizes estrogen receptor alpha (ERa) and promotes Era-mediated proliferation." (PMID 37892185, 2023). "We also identified that ERα and MINDY1 localized both in the nucleus and cytosol of breast cancer cells." (PMID 34645792, 2021). "Collectively, these results suggested that MINDY1 promoted breast cancer cell proliferation and migration, at least partially, via the stabilization of ERα." (PMID 34645792, 2021). "Depletion of MINDY1 induced G1 phases cell cycle arrest, indicating that MINDY1 was involved in the G1 to S transition of ERα-positive breast cancer cells." (PMID 34645792, 2021). "Further investigations revealed that MINDY1 promoted the proliferation and migration of breast cancer cells through ERα." (PMID 34645792, 2021). "There was a positive correlation between ERα and MINDY1 protein levels in human breast cancer tissues." (PMID 34645792, 2021). "In our present study, we investigated the biological functions of MINDY1 in ERα-positive breast cancer cells, and we identified MINDY1 as a novel post-translational modulator in the regulation of ERα deubiquitination and stabilization." (PMID 34645792, 2021). "MINDY1 depletion significantly decreased the ERα protein level and ERα signaling activity in breast cancer cells." (PMID 34645792, 2021). "An immunofluorescence assay showed that ERα and MINDY1 localized both in the nucleus and cytosol of breast cancer cells." (PMID 34645792, 2021). "To further identify MINDY1 promoted ERα-positive breast cancer cell proliferation and migration by increasing ERα stabilization, we ectopic expressed ERα in MINDY1 knockdown MCF-7 cells." (PMID 34645792, 2021). "We analyzed the public data available in bc-GenExMiner and found that MINDY1 was highly expressed in ERα-positive breast cancer samples." (PMID 34645792, 2021). "Genomic analysis of all the MINDYs in human breast cancer samples revealed MINDY1 amplification was observed in 18% of cases." (PMID 34645792, 2021). "Our data further demonstrated that MINDY1 depletion reduced ERα-positive breast cancer growth both in vitro and in vivo." (PMID 34645792, 2021). "In the present study, we identified that MINDY1, which was highly expressed in ERα-positive breast cancer samples, was a novel post-translational modulator of ERα." (PMID 34645792, 2021). "Targeting the MINDY1 may prove to be a promising strategy for patients with ERα-positive breast cancer." (PMID 34645792, 2021). "We explore if MINDY1 can improve the anti-tumor function of tamoxifen in ERα+ breast cancer cells." (PMID 34645792, 2021). "In addition, MINDY1 depletion led to growth inhibition and cell cycle arrest of ERα-positive breast cancer cells." (PMID 34645792, 2021). "It was found that MINDY1 expression was a poor prognostic factor for breast cancer patients bas." (PMID 34645792, 2021). "We further investigated the biological functions of MINDY1 in ERα-positive breast cancer cells." (PMID 34645792, 2021). "MINDY1 was highly expressed in breast cancer samples, especially in the luminal A subtype." (PMID 34645792, 2021). "Furthermore, our data demonstrated that MINDY1 may promote breast cancer progression through the expression of ERα." (PMID 34645792, 2021). "In addition, MINDY1 could promote the proliferation and migration of breast cancer cells by stabilizing ERα." (PMID 34645792, 2021). "Therefore, MINDY1 could be a potential therapeutic target for ERα-positive breast cancer." (PMID 34645792, 2021).
breast carcinoma (continued). "In the present study, we identified MINDY1, a member belongs to the motif interacting with Ubcontaining novel DUB family (MINDY), as a potential deubiquitylase of ERα in breast cancer." (PMID 34645792, 2021).
hepatocellular carcinoma (2 papers, 2024 to 2025). A malignant tumor that arises from hepatocytes. "The study aimed to investigate whether MINDY1 regulates the immune escape of hepatocellular carcinoma (HCC) mediated by PD-L1." (PMID 41179305, 2025). "However, whether MINDY1 can inhibit the stemness of hepatoma cells by deubiquitinating PD-L1 has not been reported." (PMID 39217442, 2024).
bladder tumor (1 paper, 2021). "Our data showed that MINDY1 depletion by lentivirus-based shRNA decelerated bladder tumor growth." (PMID 34315490, 2021).
brain tumors (1 paper, 2023). "The role of the evolutionarily conserved MINDY1/2 family of DUBs in brain tumors is currently unknown." (PMID 37892185, 2023).
diabetes (1 paper, 2021).
liver cancer (1 paper, 2024). An epithelial or non-epithelial malignant neoplasm that arises from the liver. "Motif interacting with ubiquitin-containing novel DUB family-1 (MINDY1), a novel deubiquitinating enzyme, is highly expressed in liver cancer tissues and maintains the stemness of liver cancer cells, which is associated with a poor prognosis of liver cancer." (PMID 39217442, 2024). "We analyzed the relationship between the expression levels of MINDY1 and PD-L1 in liver cancer tissues and their correlation with the 5-year tumor-free survival rates of patients." (PMID 39217442, 2024). "The novel deubiquitinase MINDY1 is highly expressed in liver cancer tissues and maintains the stemness of liver cancer cells." (PMID 39217442, 2024). "Their findings revealed that MINDY1 was highly expressed in liver cancer stem cells with expression levels in liver cancer tissues being higher than in adjacent tumors." (PMID 39217442, 2024). "In conclusion, MINDY1 inhibits the malignant progression of liver cancer by inhibiting PD-L1 ubiquitination and mediating immune escape." (PMID 39217442, 2024). "The novel deubiquitinase enzyme, motif interacting with ubiquitin-containing novel DUB family-1 (MINDY1), is highly expressed in liver cancer tissues and plays a crucial role in maintaining the stemness of liver cancer cells." (PMID 39217442, 2024). "In summary, MINDY1 and PD-L1 mRNA expression levels are positively correlated in liver cancer, and MINDY1 can inhibit PD-L1 ubiquitination to mediate immune escape in liver cancer, thereby preventing the malignant progression of the disease." (PMID 39217442, 2024). "We investigated the immune escape mechanism of liver cancer mediated by MINDY1 by regulating PD-L1 ubiquitination levels at the cellular level, but with limitations." (PMID 39217442, 2024). "By observing the effects of knocking down or overexpressing MINDY1 on the proliferation, apoptosis, migration, and invasion of liver cancer cells, we can systematically understand the impact and overall effect of changes in MINDY1 expression on various aspects of liver cancer cells." (PMID 39217442, 2024). "Therefore, we explored the mechanism of MINDY1 mediating liver cancer immune escape by regulating the level of PD-L1 ubiquitination, to provide a reference for clinical immunotherapy of HCC." (PMID 39217442, 2024). "Therefore, more in-depth studies are needed to provide more evidence for clinical studies on the MINDY1 gene and liver cancer immunotherapy." (PMID 39217442, 2024). "The independent effect of MINDY1 gene knockdown in liver cancer cells was demonstrated." (PMID 39217442, 2024). "However, there are limitations in this study, namely, the failure to clarify whether MINDY1 is an independent prognostic factor in HCC patients, and to detect the effects of MINDY1 and PD-L1 on tumor growth in mice with liver cancer transplantation." (PMID 39217442, 2024). "We hypothesized that after MINDY1 deletion in HCC, PD-L1 expression may be regulated through the ubiquitination modification pathway, thus affecting the immunity of the liver cancer tumor microenvironment." (PMID 39217442, 2024). "The potential role of MINDY1 in inhibiting the stemness of liver cancer cells by deubiquitinating PD-L1 has not yet been reported." (PMID 39217442, 2024).
tumor (5 papers, 2021 to 2025). "The volume and mass of tumors in the MINDY1+sh-NC group of nude mice were markedly increased, indicating that overexpression of MINDY1 can promote tumor growth." (PMID 41179305, 2025). "Ultimately, we developed a nude mouse subcutaneous xenograft tumor model to explore the impacts of MINDY1 on tumor immune escape." (PMID 41179305, 2025). "After overexpression of MINDY1, Perforin and IL-2 protein levels in tumor tissues were decreased significantly, and silencing PD-L1 caused a rise in Perforin and IL-2." (PMID 41179305, 2025). "Tumor samples exhibited a marked increase in MINDY1 expression, which corroborated the data shown in the TCGA database." (PMID 41179305, 2025). "In terms of patient prognosis, patients with high expression of MINDY1 have a higher 5-year tumor-free survival rate, while those with high expression of PD-L1 have a lower 5-year tumor-free survival rate, which is consistent with previous studies." (PMID 39217442, 2024). "Further analysis demonstrated that MINDY1 expression was correlated the ERα status, the lymph node metastasis status and tumor size." (PMID 34645792, 2021). "Based on the analysis of tissue microarrays and the Clinical Proteomic Tumor Analysis Consortium database, we observed an intimate correlation between MINDY1 expression and ERα protein level." (PMID 34645792, 2021). "Then, we used xenograft mice models to further investigated if MINDY1 promoted tumor growth in vivo." (PMID 34645792, 2021). "Then, we further investigated the role of MINDY1 in tumor growth by xenograft mice models." (PMID 34315490, 2021). "Xenograft tumor assay showed knockdown of MINDY1 markedly suppressed tumor growth." (PMID 34645792, 2021). "In this study, we examined MINDY1 levels in tumor tissues and HCC cells; MINDY1 was elevated in HCC, in agreement with findings from the TCGA database." (PMID 41179305, 2025). "This indicated that MINDY1 overexpression suppressed CD8+ T cells activation, thus weakening anti-tumor immunity mediated by CD8+ T cells." (PMID 41179305, 2025). "MINDY1 promotes PD-L1 deubiquitination and inhibits CD8+ T cell activation by stimulating the Wnt/β-catenin pathway, consequently promoting HCC tumor immune escape." (PMID 41179305, 2025). "Therefore, targeting MINDY1 may also provide a new means to inhibit tumor‐specific YAP activity." (PMID 34315490, 2021). "Knockdown of MINDY1 significantly inhibited tumor growth in vivo, while the restoration of YAP expression abolished the inhibition induced by MINDY1 depletion." (PMID 34315490, 2021).
cancer (1 paper, 2024). A tumor composed of atypical neoplastic, often pleomorphic cells that invade other tissues. "Many studies have found that high expression of MINDY1 is a risk factor for poor cancer prognosis, which is inconsistent with this study." (PMID 39217442, 2024). "The expression levels of MINDY1 and PD-L1 were significantly higher in cancer tissues (t ═ 3.949, 5.366; all P < 0.001)." (PMID 39217442, 2024). "The expression of MINDY1 in cancer tissues was positively correlated with PD-L1 (r ═ 0.540, P < 0.001)." (PMID 39217442, 2024). "The relative expression levels of MINDY1 and PD-L1 protein in cancer tissues were 6.56 ± 1.32 μg/mL and 0.75 ± 0.21 μg/mL, respectively, while in para-cancer tissues, they were 5.25 ± 1.83 μg/mL and 0.51 ± 0.18 μg/mL, respectively." (PMID 39217442, 2024). "Additionally, there was a significant difference between the high and low expression of MINDY1 in cancer tissues and the survival time of HCC patients, with patients with high expression of MINDY1 showing a trend of lower survival time." (PMID 39217442, 2024). "Our study found that the expression levels of MINDY1 and PD-L1 proteins in HCC patients’ cancer tissues were higher than those in paracancerous tissues, suggesting that MINDY1 may be a maintenance factor for HCC cells." (PMID 39217442, 2024).
MINDY1 also shares sentences with these, for which no sentence is quoted: Cirrhosis (1 paper).